NEK2 (NIMA related kinase 2)
Diseases named in the same sentence as NEK2 in open-access papers (continued):
Sharing a sentence is not in itself a finding about the gene and the disease.
breast carcinoma (continued). "Overexpression of NEK2 is observed in a number of cancers including breast cancer, pancreatic cancer, lung adenocarcinoma, cholangiocarcinoma, colorectal cancer (CRC) and non-Hodgkin lymphoma." (PMID 28881785, 2017). "Kaplan-Meier plots identified correlations between individual or combined overexpression of E2F1, E2F3a, Mps1/TTK, Nek2, BubR1, or Hec1 and poor overall and relapse-free survival of breast cancer patients." (PMID 29100415, 2017). "Further, Nek2 and Kif24 are overexpressed in breast cancer cells, and ablation of these proteins restores ciliation in these cells, thereby reducing proliferation." (PMID 26290419, 2015). "Paclitaxel and doxorubicin in combination with Nek2 siRNA or ASO treatment promote breast cancer cell apoptosis." (PMID 26320076, 2015). "Nek2 is a mitotic kinase commonly upregulated in breast cancers and a critical regulator of Cdk4- or E2F- mediated CA." (PMID 26512919, 2015). "There are many candidate genes; CENF, KIF14, DTL, NEK2, CKS1B, ASPM and EXO1 each of which are significantly associated with poor clinical outcome in breast cancer patients." (PMID 25312014, 2014). "Nek2 interacts with and phosphorylates β-catenin to regulate centrosome separation, and abnormal expression of Nek2 and β-catenin is correlated tumor proliferation in breast cancer." (PMID 25485281, 2014). "We have also found significant upregulated NEK2 expression in human breast cancer (unpublished data), which is indicated similarly in another previous study." (PMID 25202351, 2014). "Because the ubiquitin-proteasome system has been previously targeted with the proteasome inhibitor bortezomib in breast cancer, a few groups began to study and have subsequently reported that Nek2 regulates cell cycle progression in breast cancer cell lines." (PMID 25313354, 2014). "Elevated expression of Nek2 has been found in several different cancers, including breast cancer, testicular seminomas, cholangiocarcinoma, etc." (PMID 24970796, 2014). "In this report we show that Nek2 plays a key role in identifying the mechanism behind CA and binucleation in a Her2+ breast cancer model." (PMID 23776583, 2013). "This manuscript furthers the understanding of the role that CA plays in breast cancers by identifying Cdk4 and Nek2 as mediators of CA in Her2+ breast cancer cells, and by identifying binucleation as a major mechanism generating CA in breast cancers." (PMID 23776583, 2013). "To elucidate a role for Nek2 in the observed binucleation phenotype of the Her2+ breast cancer model, we stained SKBr3 and HCC1954 shNek2 cells with antibodies against α-tubulin and DAPI in order to image the cytoskeleton and nucleus, respectively." (PMID 23776583, 2013). "We conclude that CA is modulated through Cdk4 and Nek2 signaling and that binucleation is a likely source of CA in Her2+ breast cancer cells." (PMID 23776583, 2013). "Overexpression of Nek2 in immortalized breast cancer cells induces aneuploidy through multinucleated cells, and these cells are typically associated with CA." (PMID 23776583, 2013). "The subsequent filtering with the combined p-value <0.005 across 6 datasets, yielded 7 candidate genes ASPM, KIF14, NEK2, DTL, CENPF, CKS1B and EXO1 that are significantly associated with poor clinical outcome of the breast cancer patients." (PMID 24147022, 2013). "Discovering that inhibition of Nek2 or Cdk4 diminishes CA in breast cancer cells, and showing that silencing of Cdk4 leads to reduced Nek2 overexpression is important, as both molecules have been shown to mediate mammary epithelial transformation." (PMID 23776583, 2013). "Similar to the effects in breast cancer cell lines, Nek2 siRNA impaired the in vitro proliferation of the DLD-1 and Colo320 carcinoma cell lines, as well as xenografts generated by injection of DLD-1 cells." (PMID 22040655, 2011). "In breast cancer cells, NEK2 knockdown induced cell cycle arrest and led to cell death." (PMID 40220284, 2025).
breast carcinoma (continued). "Scanning the signatures in these genomic assays against the ten features used in our ‘normal’ vs. ‘cancer’ model yielded: two genes in common with Prosigna (FOXA1, MMP11), one gene with OncotypeDX (MMP11), one gene with HER2DX (NEK2), and one gene with Breast Cancer Index (NEK2)." (PMID 41048341, 2025). "Downregulation or inhibition of NEK2 suppresses the migration and invasion of breast cancer cells." (PMID 39768163, 2024). "Nek2 is an oncogene highly expressed in multiple cancers, including breast cancer." (PMID 39610830, 2024). "NEK2 is essential for breast carcinoma carcinogenesis, tumor invasion, and tumorigenic growth." (PMID 38895505, 2024). "Specifically: 1) NEK2 is a constituent of the 11-gene Breast Cancer Index signature used to estimate recurrence; and 2) MMP11 is a constituent biomarker of the 50-gene Prosigna, and 21-gene OncotypeDX signature panels, which are both used in estimating likelihood of recurrence." (PMID 37287543, 2023). "In addition, we have published that the overexpression of Nek2 or TTK mRNA is associated with poor overall- and relapse-free survival of breast cancer patients." (PMID 36494865, 2022). "Since the cell cycle is one of the most commonly deregulated cellular processes in cancer, we propose that the mitotic kinases TTK (or Mps1), TBK1, and Nek2 could be novel targets to prevent breast cancer progression among NHBs and H/Ls." (PMID 36494865, 2022). "Finally, Sam68 has been recently shown to be phosphorylated by Nek2 in breast cancer cell lines and, like Erk1, Nek2-mediated phosphorylation of Sam68 stimulated its activity towards CD44 exon 5 inclusion." (PMID 36537190, 2022). "Collectively, the current study indicated that NEK family genes, especially NEK2 which is involved in immune infiltration, and may serve as prognosis biomarkers for breast cancer progression." (PMID 34834441, 2021). "These analytical data suggest that NEK2 may be involved in the recurrence of Basal-, LumA- and LumB-subtype breast cancer, while NEIL3 and CDC25C may only be involved in recurrence of LumA-subtype breast cancer." (PMID 33644115, 2021). "Therefore, NEK2 has the potential as a prognostic biomarker for immune infiltration in breast cancer development." (PMID 34834441, 2021). "Meanwhile, a previous study revealed that NEK2 has distinctly essential roles as a tumor-suppressor gene in different cancers, such as lung adenocarcinoma, ovarian cancer, hepatocellular carcinoma, and breast cancer." (PMID 34834441, 2021). "Besides its role in CA/CIN, Nek2 contributes to breast cancer progression through a novel EMT mediated mechanism." (PMID 33907253, 2021). "We identified that Nek2 overexpression correlates with poor survival of breast cancer." (PMID 33907253, 2021). "Furthermore, analysis of miRNA-regulated networks with NEK2 also suggested that hsa-miR-1236-3p, hsa-miR-4264, hsa-miR-486-5p, hsa-miR-155-3p, and hsa-miR-6839-3p are also regulated breast cancer development." (PMID 34834441, 2021). "Inappropriate expression of NEK2 interfere with mitotic processes results in breast cancer development, but this gene might be play key role in pathogenesis of pituitary prolactinoma." (PMID 33709028, 2021). "However, none of these studies included breast cancer; therefore, here we explore the role of Nek2 in driving breast cancer EMT." (PMID 33907253, 2021). "In conclusion, NEK2 may have potential value as a prognostic and immune infiltration marker for breast cancer development." (PMID 34834441, 2021). "However, Nek2 can help sustain tumorigenesis, illustrated by observations that Nek2 depletion in mouse models significantly reduces mammary tumor growth." (PMID 33907253, 2021).
breast carcinoma (continued). "Although both miR‐128‐3p and NEK2 have been studied in the growth of breast cancer, their exact roles in breast cancer remain unclear." (PMID 32558224, 2020). "Patients with breast cancer were selected and the levels of NEK2 mRNA were accessed." (PMID 32294979, 2020). "Additionally, NEK2 is overexpressed in Her2-positive breast cancer cells with centrosome amplification." (PMID 32294979, 2020). "Moreover, NEK2 deregulation was found to act as drivers of tumorigenesis in breast cancer by induction of centrosome amplification." (PMID 32504181, 2020). "Studies have shown that the high mRNA expression of NEK2 was related to the incidence, differentiation, metastasis and prognosis of multiple myeloma, pancreatic ductal adenocarcinoma, ovarian cancer, colorectal cancer and breast cancer." (PMID 33109182, 2020). "The expression level of NEK2 gene was further analysed in breast cancer samples included by The Cancer Genome Atlas (TCGA), showing that the expression level of NEK2 gene was significantly up‐regulated in the breast cancer samples at different stages compared with the control group." (PMID 32558224, 2020). "In addition, a previous study has shown that the expression of NEK2 is always up‐regulated in breast cancer." (PMID 32558224, 2020). "Furthermore, analyses in breast cancer cells showed that the depletion of NEK2 induces aneuploidy, alteration in the centrosome, deregulation in the cell cycle, and increased apoptosis." (PMID 32294979, 2020). "Therefore, this study was designed to investigate the specific relationship between miR‐128‐3p and NEK2 and their effects on the development of breast cancer." (PMID 32558224, 2020). "Similarly, one study has demonstrated that miR-128-3p inhibits the stem-like cell features of BCSCs via inhibition of the Wnt signaling pathway by downregulating NEK2, which provides a new target for breast cancer treatment." (PMID 33008330, 2020). "In the present study, we hypothesized that overexpression of miR‐128‐3p may regulate the biological characteristics including proliferation, migration and invasion of breast cancer stem cells (BCSCs) by mediating the expression of NEK2." (PMID 32558224, 2020). "NDC80 might be a good targeting option in suppressing breast cancer tumor growth, and dual targeting of NEK2 and NDC80 might improve the prognosis." (PMID 33109182, 2020). "Highly expressed NEK2 was found in breast cancer based on GSE61304 expression profile." (PMID 32558224, 2020). "On contrast, NEK2 knockdown could significantly inhibit the proliferation, colony formation, invasiveness, and in vivo growth of breast cancer cells." (PMID 30578380, 2019). "The fact that multiple different tumorigenic behaviors were affected by perturbing CEP55 expression suggests that, like other mitotic proteins [e.g., Aurora‐A, Eg5, PLK1, NEK2], it could regulate multiple aspects of breast cancer development." (PMID 30108112, 2018). "Likewise, Her2+ breast cancer cells require Cdk4 and Nek2 to signal centrosome amplification and chromosome instability." (PMID 30381801, 2018). "Also, silencing of cyclin dependent kinase 4 (CDK4) in Her2+ breast cancer cells resulted in diminished levels of NEK2." (PMID 28881785, 2017). "Suppression of the NEK2 expression with siRNA inhibited cell proliferation and induced cell death of breast cancer, cholangiocarcinoma, colorectal cancer, multiple myeloma, hepatoma and prostate cancer cells in vitro, and led to a reduction of tumor size in xenograft-nude mouse model." (PMID 27764815, 2016). "NEK2 has been reported to be overexpressed in a wide variety of human cancers, such as gastric cancer, colorectal cancer, prostate cancer and breast cancer." (PMID 27764815, 2016). "Moreover, silencing of NEK2 expression in breast cancer and colorectal cancer cells dramatically increased the susceptibility to chemotherapeutic drugs, such as paclitaxel, doxorubicin and cisplatin." (PMID 27764815, 2016).
breast carcinoma (continued). "Finally, we found that depletion of either Nek2 or Kif24 in breast cancer cell lines restored ciliation and reduced proliferation of these cells." (PMID 26290419, 2015). "Furthermore, abrogating this defective Nek2/Kif24 activation can restore primary cilia formation and restrict proliferation in breast cancer cells." (PMID 26290419, 2015). "Furthermore, breast cancer patients with both Ndc80 and Nek2 overexpression display shorter survival compared to patients with only either Ndc80 or Nek2 overexpression." (PMID 25557589, 2015). "Therefore, we compared the expression levels of Kif24 and Nek2 in a panel of breast cancer cell lines with the normal human mammary epithelial cell line (HMEC) as control." (PMID 26290419, 2015). "Furthermore, suppression of Nek2 results in the decreased viability of cancer cells in solid cancers, like breast cancer, non-small cell lung cancer, colorectal cancer, ovarian cancer, and liquid cancers like myeloma." (PMID 25485281, 2014). "Nek2 levels have been found to be elevated in human breast cancer." (PMID 23776583, 2013). "Thus, NEK2 is markedly upregulated in human breast cancer tissues, correlating with a poor prognosis, and holds promise as a potential biomarker for identifying breast cancer." (PMID 37627077, 2023). "In the present study, we evaluated mRNA expression patterns of the mitotic kinases Nek2, Mps1/TTK, and TBK1, as well as the expression and association of these proteins with biomarkers of proliferation (Ki67) and EMT (E-cadherin and Vimentin) by using a novel breast cancer TMA." (PMID 36494865, 2022). "Finally, we identified NEK2 as a potential biomarker of immune cells in breast cancer tissues." (PMID 34834441, 2021). "Thus, NEK2 represents a novel target for breast cancer treatment." (PMID 34360879, 2021). "Similarly, NEK3 and NEK2 were found to be over-expressed, in human breast cancer." (PMID 31906878, 2020). "Moreover, high levels of NEK2 protein expression were detected in breast cancer patients." (PMID 32294979, 2020). "In addition, NEK2, which could alter cell migration, has been proven to be one of the most predictive genes that are related to metastasis‐free survival in breast cancer." (PMID 32558224, 2020). "Moreover, silencing NEK2 was demonstrated to sensitize triple-negative breast cancer cells to paclitaxel and doxorubicin, which indicated that NEK2 may be potential therapeutic target for breast cancer." (PMID 30578380, 2019). "Finally, NEK2 codifies for a serine–threonine kinase with a key role in mitosis that has been found to be aberrantly overexpressed in several cancer types, among them breast cancer." (PMID 29330624, 2018). "By normalizing the expression profiles of Kif24 and Nek2 with HMECs, we found that Kif24 protein levels were comparable or modestly elevated across the panel of cell lines, whereas Nek2 was strongly upregulated (∼5–30-fold) in all breast cancer cell lines that we examined." (PMID 26290419, 2015). "Commonality with most of the short-listed genes (CENPF, KIF14, NEK2, CKS1B and ASPM) is their positive association with proliferation marker Ki-67, thereby, indicating their possible role in cell cycle related dysregulations and the resultant proliferation of breast cancer cells." (PMID 24147022, 2013). "Together, these data demonstrate that dual targeting of NEK2 and CDK4/6 disrupts the ability of breast cancer cells to successfully complete mitosis." (PMID 39826695, 2025). "Data from clinical breast cancer samples indicate that the combined detection of TUFT1 and NEK2 expression reflects tumor malignancy and patient survival with higher precision." (PMID 41022752, 2025). "It is therefore particularly striking that dual targeting of NEK2 and CDK4/6 is effective at augmenting CIN and repressing cell growth in both models of breast cancer." (PMID 39826695, 2025).
breast carcinoma (continued). "We further assessed the correlation between NEK2/TUFT1 expression and the overall survival (OS) of patients with breast cancer based on Kaplan-Meier Plotter databases." (PMID 41022752, 2025). "NEK2 expression negatively correlated with OS only in the TUFT1 high-expression group, indicating that NEK2 drives breast cancer progression by regulating TUFT1." (PMID 41022752, 2025). "We examined the TCGA dataset to understand the differences in the mRNA expression of Nek2, TTK, and TBK1 in NHW (n = 743), NHB (n = 187), and H/L (n = 39) populations with breast cancer based on their self-reported race and ethnicity." (PMID 36494865, 2022). "This analysis indicates that the mRNA levels of multiple mitotic regulators, including TTK, Nek2, PLK1, Cyclin B1, BUB1, Aurora kinases A and B, and NDC80 (also known as HEC1) are elevated in breast cancers in NHB women." (PMID 36494865, 2022). "In line with the previous observations, INH154 effectively reduced the Nek2 levels in human breast cancer cell lines, MDA-MB-468 and MDA-MDA-MB-231, and abolished Nek2-mediated HEC1-S165 phosphorylation." (PMID 35056661, 2022). "In one study, Nek2 over-expressions in MDA-MB-231 and MCF7 breast cancer cells resulted in mitotic aberrations such as abnormal centrosome contents and multinucleated cells." (PMID 35056661, 2022). "In investigating the epigenetic regulation and mechanisms involved in BCSC, NIMA-related kinase 2 (NEK2) has been identified as a novel target of miR-128-3p, and is upregulated in breast cancer." (PMID 34360879, 2021). "We found a significant result in the survival analysis, which revealed that NEK2/6/8 had high HRs and overexpression prognostic significance in DMFS in breast cancer patients." (PMID 34834441, 2021). "We found a significant result in the survival analysis, which revealed that NEK2/6/8 have high HRs and overexpression prognostic significance in DMFS in breast cancer patients." (PMID 34834441, 2021). "DNA methylation expression levels concluded that cg17931972 from NEK2 and cg14289738 from NEK6 had the highest DNA methylation levels and significant prognostic value (likelihood ratio (LR) test p-value < 0.05) in breast cancer." (PMID 34834441, 2021). "Here, we found that low expression of NEIL3, CDC25C, and NEK2 predicted high RFS and OS respectively (p < 0.05), and low expression of HCN2 predicted high OS (p < 0.05) in all breast cancer." (PMID 33644115, 2021). "Four kinases-serine/threonine-protein kinase Nek2 (NEK2), aurora kinase A (AURKA), cyclin-dependent kinase 1 and 2 (CDK1 and CDK2) were the predicted to be activated across breast cancer, colon cancer, LUAD, ovarian cancer, and UCEC." (PMID 32033228, 2020). "With a combined integrative and bioinformatics approach, we identified the dysregulation in the cell cycle pathway and predicted the activation of NEK2 and AURKA across breast cancer, colon cancer, LUAD, ovarian cancer, and UCEC." (PMID 32033228, 2020). "Our study provides the insights into the altered cell cycle signaling pathway and predicts NEK2 and AURKA kinases to be activated in breast cancer, colon cancer, LUAD, ovarian cancer, and UCEC." (PMID 32033228, 2020). "Breast cancer cells, MDA-MB-231, and MCF7, were treated with TRF1 siRNA, and NEK2 was overexpressed concomitantly." (PMID 32294979, 2020). "The expression of NEK2, NEK6, and NEK11 were related to colorectal cancer, NEK2, NEK3, NEK5, NEK6, and NEK8 to breast cancer, and NEK2 and NEK6 to prostate cancer." (PMID 31906878, 2020). "Our laboratory has demonstrated that deregulation of regulators of the centrosome cycle, mitosis, and G1/S phase including Cdk4, the E2F activators (E2F1, E2F3a), Nek2, Sgo1, and Mps1/TTK are required to maintain high CA and CIN in Her2+ breast cancer cells." (PMID 29100415, 2017).